ASCC3 (activating signal cointegrator 1 complex subunit 3)
Diseases named in the same sentence as ASCC3 in open-access papers (continued):
Sharing a sentence is not in itself a finding about the gene and the disease.
cancer (10 papers, 2017 to 2026). A tumor composed of atypical neoplastic, often pleomorphic cells that invade other tissues. "Here, the authors identify a minimal stable complex of the two ASCC subunits ASCC2 and ASCC3, determine the complex crystal structure and further show that cancer-related mutations at the interface between both proteins reduce ASCC2–ASCC3 affinity." (PMID 33139697, 2020). "Furthermore, mutations of ASCC3 in pan-cancer were investigated using the PFAM and CbioPortal databases." (PMID 40881169, 2025). "We also analyzed the association between ASCC3 expression and prognosis in other cancer types." (PMID 40881169, 2025). "The affinity between DNA repair factors ASCC2 and ASCC3 is reduced by cancer mutations." (PMID 34299277, 2021). "Moreover, due to ASCC3’s involvement in DNA repair functions, the genomic repair capacity and stability of older patients are greatly reduced, increasing their risk of cancer and mortality." (PMID 40881169, 2025). "To examine the role of endogenous circASCC3, we depleted its expression using two independent siRNAs in various cancer cells, while the expression of ASCC3 remained unaffected." (PMID 40067902, 2025). "Using TIMER database data, we analyzed the expression of ASCC3 gene in pan-cancer based on TCGA sample." (PMID 40881169, 2025). "To investigate the role of ASCC3 in various types of digestive system cancers, we performed GSVA analysis to examine the correlation between ASCC3 expression and different functional states in 14 types of cancer." (PMID 40881169, 2025). "Furthermore, we analyzed the mutation status of ASCC3, JAK1, NFKB1, SEMA5A, NR2C2, CNTF and CREB1 across pan-cancer." (PMID 40881169, 2025). "The role of ASCC3 varies across different cancer types, which may be related to its function in DNA repair and maintaining genomic stability." (PMID 40881169, 2025). "In addition, we downloaded the protein expression data for ASCC3 from the TCPA database and calculated the differences in the activity scores of 10 cancer pathways associated with high ASCC3 expression." (PMID 40881169, 2025). "Relevant studies suggest that high ASCC3 expression may repair chemotherapy-induced DNA damage, enhancing cancer cell survival and indirectly promoting tumor progression." (PMID 40881169, 2025). "Indeed, ASCC3 is overexpressed in several cancers and ASCC3 knockdown, which would be expected to lead to less efficient AlkBH3-mediated DNA de-alkylation repair, has been shown to negatively impact tumor cell proliferation in culture and xenograft models." (PMID 33139697, 2020). "To investigate the mutation distribution of the ASCC3 gene across pan-cancer, we first explored the mutation hotspots of ASCC3 using the PFAM database, and subsequently analyzed the mutation frequency differences of ASCC3 across pan-cancer based on the Cbioportal database." (PMID 40881169, 2025). "Furthermore, ASCC3 expression shows significant prognostic differences across various cancer types." (PMID 40881169, 2025). "Moreover, we observed that a large number of ASCC2 and ASCC3 residue substitutions encoded by somatic mutations in cancers map to ASCC2–ASCC3 interface regions and that selected, cancer-related residue substitutions in ASCC3 lead to reduced ASCC2–ASCC3 affinity." (PMID 33139697, 2020). "An activating signal co-integrator complex subunit 3 (ASCC3) is a DNA helicase and unwinding by ASCC3 is coupled with ALKBH3-dependent DNA alkylation repair and cancer cell proliferation in mammalian cells." (PMID 28757607, 2017).
cancer (continued). "Notably, the expression profile of various RQC factors (e.g., ASCC3, ABCE1, ANKZF1, and VCP) is dysregulated in cancer." (PMID 38798583, 2026). "The inhibition of ABCE1, ASCC3, and VCP has been shown to impede cancer cell proliferation and viability, while inhibiting NEMF/Clbn and ZNF598 may facilitate cancer cell growth and survival." (PMID 40785597, 2025). "In addition, circASCC3 was more stable than the linear transcripts of ASCC3 and CDKN1A (usually known as p21), as it exhibited prolonged half-life in cancer cells when transcription was blocked by Actinomycin D and was resistant to RNase R digestion." (PMID 40067902, 2025). "Furthermore, the dysregulation of RQC factor expression in cancer cells, including that of ASCC3, ANKZF1, ABCE1, and VCP, highlights the intricate nature of their roles in cancer." (PMID 39315278, 2024). "For example, ASCC3, ABCE1, ANKZF1, VCP have been shown to be overexpressed in cancer cells." (PMID 36187485, 2022). "Functional studies have shown that inhibition of ABCE1, ASCC3, and VCP may inhibit cancer cell growth and survival, whereas inhibition of NEMF/Clbn and ZNF598 may have opposite effects." (PMID 36187485, 2022). "Interestingly, RQC factors can display opposing functions in cancer development and suppression depending on specific circumstances, with some factors like ABCE1, ASCC3, and VCP suppressing cancer cell growth upon downregulation, while others like NEMF/Clbn and ZNF598 may promote it upon inhibition." (PMID 38798583, 2026). "Initial omics‐based analyses have shown dysregulation in the expression of several RQC genes, such as ASCC3, ABCE1, ANKZF1, and VCP, in cancer cells; however, there is a lack of direct mechanistic studies." (PMID 40785597, 2025).
tumor (4 papers, 2018 to 2025). "To identify genes potentially associated with ASCC3 in rectal cancer and investigate its role in the tumor microenvironment, we selected ASCC3-related differentially expressed genes (DEGs) from TCGA rectal cancer samples." (PMID 40881169, 2025). "This suggests that ASCC3 may participate in repairing damage to immune-positive regulatory cells associated with T cells, thereby maintaining anti-tumor immune efficacy and inhibiting tumor immune evasion." (PMID 40881169, 2025). "Except for age, the expression of ASCC3 in tumor tissues was higher than in normal tissues for gender, T stage, N stage, M stage and pathological stage." (PMID 40881169, 2025). "These pathways are known to be involved in cell proliferation and differentiation, suggesting that ASCC3 may also affect the tumor microenvironment by regulating cell proliferation and differentiation." (PMID 40881169, 2025). "ASCC3 may influence patient prognosis in conjunction with multiple immune-related genes and could enhance anti-tumor immunity by regulating T cell immune functions." (PMID 40881169, 2025). "Therefore, we infer that ASCC3 mainly enhances immune function by modulating T cell immune activity, thereby exerting a protective anti-tumor effect." (PMID 40881169, 2025). "ASCC3, in conjunction with various immune-related genes, may influence patient prognosis and potentially enhance anti-tumor immunity by regulating T cell immune functions." (PMID 40881169, 2025). "The frequency of double allelic alterations in SHPRH and ASCC3 suggest that they may be candidate tumor suppressor genes in LUAD, whereby their inactivation could contribute to LUAD development and progression." (PMID 38890444, 2024). "The results slightly differed from those of TCGA, with ASCC3 and ASCC1 being more highly expressed in tumor tissue, while ASCC2 and TRIP4 were significantly expressed in normal tissue." (PMID 40881169, 2025). "Furthermore, ASCC3 may regulate tumor immunity by affecting T cell function." (PMID 40881169, 2025). "Therefore, we hypothesize that ASCC3 exerts its antitumor immune effects and provides protective effects primarily by coordinating the immune roles of different types of CD4+ T cells, CD8+ T cells, M2 macrophages, and Tregs in the tumor microenvironment." (PMID 40881169, 2025).
digestive system cancer (1 paper, 2025). A primary or metastatic malignant neoplasm involving any part of the digestive system. "In addition, we also evaluated the association between ASCC3 expression and patient OS in various digestive system cancers." (PMID 40881169, 2025). "We analyzed the impact of ASCC3 expression on the prognosis of patients with various digestive system cancers." (PMID 40881169, 2025).
infection (1 paper, 2017). The state of being infected such as from the introduction of a foreign agent such as serum, vaccine, antigenic substance or organism. "ASCC3 was also identified in a screen for genes affecting infection of West Nile virus in interferon (IFN)-β-treated human cells, with silencing of ASCC3 resulting in upregulation of certain interferon-stimulated genes." (PMID 28215706, 2017).
neurodegenerative disease (1 paper, 2017). A disorder of the central nervous system characterized by gradual and progressive loss of neural tissue and neurologic function. "This evidence suggested that DLG2 and ASCC3 might have pleiotropic effects on putamen and neurodegenerative diseases; on the other hand, they might influence neurodegenerative diseases through alteration of putamen." (PMID 29147026, 2017).
neurodevelopmental disorder (1 paper, 2024). A behavioral and cognitive disorder with onset during the developmental period that involves impaired or aberrant development of intellectual, motor, or social functions. "Activating Signal Cointegrator 1 Complex, Subunit 3 (ASCC3) has been implicated in the pathogenesis of neurodevelopmental disorders and neuromuscular diseases (MIM: 620700)." (PMID 39286456, 2024).
ASCC3 also shares sentences with these, for which no sentence is quoted: Chronic Hepatitis B (1 paper); clear cell renal carcinoma (1); Cockayne syndrome B (1); Cognitive impairment (1); colon adenocarcinoma (1); endocervical adenocarcinoma (1); endometrial cancer (1); esophageal carcinoma (1); neurological disorders (1); neuromuscular disease (1); pancreatic adenocarcinoma (1).